SDC2 (syndecan 2)
Diseases named in the same sentence as SDC2 in open-access papers (continued):
Sharing a sentence is not in itself a finding about the gene and the disease.
heart failure (2 papers, 2021 to 2025). Inability of the heart to pump blood at an adequate rate to meet tissue metabolic requirements. "Second, SDC2 gene expression is important, but also the presence of sequence-altering mutations is a potentially important indicator of causal association with heart failure." (PMID 40149456, 2025). "Future studies are warranted to explore the potential contribution of SDC2 mutations to metabolic imbalances or heart failure." (PMID 40149456, 2025). "This opens up an exciting avenue for future research, where SDC2 could be explored as a novel therapeutic target, particularly given its involvement in the metabolic pathways that contribute to heart failure pathogenesis." (PMID 40149456, 2025). "In addition, we identified SDC2 as a potential key gene involved in heart failure." (PMID 40149456, 2025).
hyperplastic polyp (2 papers, 2017 to 2019). A polyp found mainly in the stomach and colon. "Bowel lavage fluid (BLF) SDC2 methylation data showed that SDC2 methylation was positive in 100% of villous adenoma, high-grade dysplasia, and hyperplastic polyp samples; in 88.9% of tubular adenoma samples; and in 0% of normal mucosal samples." (PMID 31182980, 2019).
liver cancer (2 papers, 2019 to 2020). An epithelial or non-epithelial malignant neoplasm that arises from the liver. "For gastric and liver cancers, detection rates of SDC2 methylation were 30.4% (7/23) and 30 (3/10), respectively." (PMID 30876480, 2019). "Hence, it is crucial to define the effects of interfering diseases, in particular the malignancies of the digestive tract including esophageal, gastric, pancreatic, and liver cancers, on the detection accuracy of fecal SDC2 methylation test." (PMID 33126908, 2020). "To determine CRC-specific methylation of SDC2, we also enrolled liver cancer patients." (PMID 30876480, 2019).
malignant mesothelioma (2 papers, 2009 to 2013). A malignant neoplasm of the pleura or peritoneum, arising from mesothelial cells. "Malignant mesothelioma cells also synthesize syndecan-2 and -4 and these syndecans, less often expressed in carcinomas, are especially abundant in the epithelioid phenotype." (PMID 24392351, 2013). "Thus syndecan-1 and syndecan-2 has been proposed as biomarkers to distinguish malignant mesothelioma from metastatic adenocarcinoma." (PMID 24392351, 2013).
myeloma (2 papers, 2012 to 2023). "Expression of mRNA encoding syndecan-2 and -3 was only found in the myeloma cell lines U-266 and KMS-5, however the U-266 cells showed a low expression of syndecan-2 mRNA compared to KMS-5 and no expression of syndecan-3 mRNA." (PMID 22777011, 2012).
ovarian carcinoma (2 papers, 2025). A malignant neoplasm originating from the surface ovarian epithelium. "MDK secreted from ovarian cancer epithelial cells can also regulate cancer-associated fibroblasts by binding to NCL/syndecan 2 (SDC2)/LRP1." (PMID 40429950, 2025).
pancreatic adenocarcinoma (2 papers, 2012 to 2015). "SDC2 is a novel PNI-associated gene in pancreatic adenocarcinoma cases, with SDC2 silencing markedly reducing the motility and invasiveness of the cancer cells." (PMID 26576639, 2015). "We have identified syndecan-2 as a protein potentially involved in perineural invasion of pancreatic adenocarcinoma (PDAC) cells." (PMID 22471946, 2012).
periodontitis (2 papers, 2019 to 2024). An acute or chronic inflammatory process that affects the tissues that surround and support the teeth. "Column graphs reveal that the total distribution of Sdcs and HPSE1 is almost equal in periodontitis group compared to controls, but the pattern of this distribution between epithelial and stromal compartments of gingival tissue (except for Sdc2) are quite different." (PMID 31611818, 2019).
sarcoma (2 papers, 2012 to 2013). A usually aggressive malignant neoplasm of the soft tissue or bone. "Moreover, syndecan-2 is crucial for the tumorigenic activity of sarcoma cells and this function relies on FAK-mediated signaling." (PMID 23705906, 2013).
squamous cell carcinoma (2 papers, 2022 to 2023). A carcinoma arising from squamous epithelial cells. "ARID1A significantly inhibits the proliferation and progression of squamous cell carcinoma via mediating with SDC2, WNT, Akt and Ras signaling pathways." (PMID 35715413, 2022). "Targeting Trim32/USP11/ARID1A/SDC2 might be a potential therapeutic strategy for patients with squamous cell carcinoma." (PMID 35715413, 2022).
systemic sclerosis (2 papers, 2012 to 2019). A chronic disorder, possibly autoimmune, marked by excessive production of collagen which results in hardening and thickening of body tissues. "Syndecan-2 has been revealed to bind to TGF-β and increase its signaling, and is overexpressed in the fibrotic lung tissues of patients with systemic sclerosis and IPF." (PMID 31600983, 2019).
aneurysm (1 paper, 2025). Bulging or ballooning in an area of an artery secondary to arterial wall weakening. "It encompasses four components: syndecan-1, syndecan-2, and syndecan-4 (with syndecan-3 only expressed in neural tissue), which have a fundamental role in regulating the events of acute and chronic aorta damage subsequently correlated with the formation of aneurysms." (PMID 39940978, 2025).
asthma (1 paper, 2022). "According to microarray data, SDC2 expression was higher in diseases with an M2-like phenotype, such as asthma, while in vitro generated M1-like macrophages possessed downregulated SDC2 expression." (PMID 36359389, 2022).
Autoimmunity (1 paper, 2025). The occurrence of an immune reaction against the organism's own cells or tissues. "For instance, IFN alpha and gamma regulate ER dependent function in antigen presentation, suggesting that the TMEM230/RNASET2/SDC2/IRF1 axis is mis regulated both in autoimmunity and cancer." (PMID 40862725, 2025).
Azoospermia (1 paper, 2024). Absence of any measurable level of sperm,whereby spermatozoa cannot be observed even after centrifugation of the semen pellet. "In addition, we found downregulation of PTN and SDC2 as well as altered localization in non-obstructive azoospermia (NOA) patients, suggesting that downregulation of PTN and SDC2 may be associated with impaired spermatogenesis." (PMID 39285301, 2024).
bacterial pneumonia (1 paper, 2022). Acute infection of the lung parenchyma caused by bacteria (e.g., Streptococcus pneumoniae, Haemophilus influenzae, Chlamydia pneumoniae, Mycoplasma pneumoniae, and Legionella pneumophila). "Recently, using SDC2 as a marker on the surface of hMSCs, investigators identified a population of cells that was beneficial against bacterial pneumonia and ventilator‐induced lung injury." (PMID 34355516, 2022).
cervical cancer (1 paper, 2022). A primary or metastatic malignant neoplasm involving the cervix. "As a result, the overexpression of circNFATC3 in cervical cancer leads to the overexpression of SDC2 and its downstream targets syntenin-1, NF-κB, and MMP-9." (PMID 36358747, 2022). "Finally, circNFATC3, a circular RNA that is overexpressed in cervical cancer, works as a molecular sponge for miR-9-5p, which is a suppressor of SDC2 expression." (PMID 36358747, 2022).
cervical disease (1 paper, 2023). "In current study, we also found that SNP sites rs16894821 and rs724236 in SDC2 gene were associated with the susceptibility to HPV, and rs16894821 was related with the cervical disease." (PMID 37358427, 2023).
chronic pancreatitis (1 paper, 2012). A chronic inflammatory process causing damage and fibrosis of the pancreatic parenchyma. "Syndecan-2 (SDC-2) expression was analyzed in human normal pancreas, chronic pancreatitis and PDAC tissues." (PMID 22471946, 2012).
cross-infection (1 paper, 2021). "As a non-invasive detection method, SDC2/TFPI2-joined detection in stool samples is safe and can be operated easily, avoiding bowel preparation and possible cross-infection during colonoscopy." (PMID 35004840, 2021).
depression (1 paper, 2025). "SDC2, on the other hand, is a member of the syndecan family, involved in cell binding, cell signalling, and cytoskeletal organisation, which we identified in association with current depression via MAGMA gene-based tests, drawing on our results from the genome-wide by trait interaction analysis." (PMID 40157903, 2025).
dilated cardiomyopathy (1 paper, 2025). Cardiomyopathy which is characterized by dilation and contractile dysfunction of the left and right ventricles. "An integrated bioinformatics analysis was performed to investigate the function of heparan sulfate in dilated cardiomyopathy, which revealed that SDC2 was strongly correlated with collagen I and collagen III in the cardiac fibroblasts of hearts with dilated cardiomyopathy." (PMID 40149456, 2025).
epithelioid mesothelioma (1 paper, 2013). "In epithelioid mesothelioma cells, syndecan-2 is mainly found in the cytoplasm, while syndecan-1 is mainly located at the cell membrane, from where it may be shed into extracellular fluids." (PMID 23991032, 2013).
femoral neck fracture (1 paper, 2024). Fractures of the short, constricted portion of the thigh bone between the femur head and the trochanters. "The immunohistochemical expressions of SDC1, SDC2, SDC4, EXT1, EXT2, NDST1 and NDST2 in synovial intima and subintima were then analysed and compared with the control group (patients with femoral neck fracture)." (PMID 38674142, 2024).
glomerulosclerosis (1 paper, 2012). A hardening of the kidney glomerulus caused by scarring of the blood vessels. "SDC2 expression is increased in the tubulo-interstitium of kidneys from type II diabetic patients, and its inducible role in fibrosis has been demonstrated in Syndecan 4 deficient mice, where SDC2 is up-regulated in parallel with TGFβ during unilateral nephrectomy-induced glomerulosclerosis." (PMID 22900087, 2012).
hemophilia A (1 paper, 2025). The most common form of hemophilia characterized by spontaneous or prolonged hemorrhages due to factor VIII deficiency. "The results showed two drugs targeting SDC2: Palifermin, which is used for the prevention and treatment of oral mucositis, and Efanesoctocog alfa, which is indicated for the treatment of hemophilia A. However, to date, no drugs targeting SDC2 for the treatment of HF have been developed." (PMID 40149456, 2025).
hilar cholangiocarcinoma (1 paper, 2023). A cholangiocarcinoma that arises from the junction, or adjacent to the junction, of the right and left hepatic ducts. "What’s more, the M2 splice isoform of PK (PKM2) was found to regulate neural invasion of hilar cholangiocarcinoma (HC) via regulation of SDC2." (PMID 36418844, 2023).
inflammatory bowel disease (1 paper, 2019). A spectrum of small and large bowel inflammatory diseases of unknown etiology. "Further studies are also needed to perform meSDC2 LTE-qMSP test using stool DNA samples from patients with inflammatory bowel disease (IBD) to determine the potential influence of exfoliation of methylated SDC2 DNA from small neoplasms in IBD on test results." (PMID 30876480, 2019).
interstitial cystitis (1 paper, 2025). A rare chronic debilitating urogenital disease characterized by urinary frequency, urgency, and pelvic pain. "We found that heparanase 1 (HPSE) and syndecan-1 (SDC-1), syndecan-2 (SDC-2) and syndecan-4 (SDC-4) within the SDC family were up-regulated in the interstitial cystitis/bladder pain syndrome (IC/BPS) tissues." (PMID 40408331, 2025).
interstitial lung disease (1 paper, 2025). A diverse group of lung diseases that affect the lung parenchyma. "In rheumatoid arthritis -associated interstitial lung disease, elevated PAD2 expression in lung fibroblasts promoted a pro-fibrotic phenotype, while overexpression of syndecan-2 (SDC2) inhibited PAD2 and protected against BLM-induced fibrosis." (PMID 40858556, 2025).
intestinal tumors (1 paper, 2025). "Moreover, recent studies have found that SDC2 stimulates the migration of cancer cells during the development of intestinal tumors, and its methylation level has shown high diagnostic value and prognostic significance in intestinal tumors." (PMID 40149456, 2025).
leukemia (1 paper, 2024). A malignant (clonal) hematologic disorder, involving hematopoietic stem cells and characterized by the presence of primitive or atypical myeloid or lymphoid cells in the bone marrow and the blood. "Combined multi-omics data pinpointed three upregulated genes (SDC2, NCAM2, and IFI44) that showed negative effects on survival in a larger leukemia cohort." (PMID 39399221, 2024).
malaria (1 paper, 2019). Malaria is a serious and sometimes fatal disease caused by a parasite that commonly infects a certain type of mosquito which feeds on humans. "Malaria disease was the single KEGG pathway identified and this was linked to IL6, syndecan-2 (SDC2) and thrombospondin-1 (THBS1) DEGS that were enriched in the down-regulated gene set." (PMID 31792230, 2019).
metastasis (1 paper, 2023). The spread or migration of cancer cells from one part of the body (where they first appeared) to another. "Moreover, the GC patients with higher N stages also had a higher expression of SDC2 compared to those with low N stages and primary GC tumors without lymph node metastasis." (PMID 37496999, 2023).
myeloid leukemia (1 paper, 2020). A clonal proliferation of myeloid cells and their precursors in the bone marrow, peripheral blood, and spleen. "We should note that other syndecan family members may also contribute to myeloid leukemia, since knockdown of SDC2, SDC3, SDC4 either individually or in combination led to significant growth inhibition." (PMID 33243988, 2020).
nasopharyngeal carcinoma (1 paper, 2023). A carcinoma arising from the nasopharyngeal epithelium. "In nasopharyngeal carcinoma, LMP-1 increases the packaging of hypoxia-inducible factor 1α (HIFα) into EVs and the secretion of EVs through syndecan-2 (SDC2) and synaptotagmin-like-4 (SYTL4)—NFκB pathway." (PMID 36674550, 2023).
psoriasis (1 paper, 2020). An autoimmune condition characterized by red, well-delineated plaques with silvery scales that are usually on the extensor surfaces and scalp. "SDC2, a target of miR-665 and miR-1207-5p, was found to be upregulated in the blood and lesions of psoriasis patients and to be involved in angiogenesis and the migration and retention of leukocytes." (PMID 32411787, 2020).
pterygium (1 paper, 2022). A wedge-shaped fibrovascular lesion arising from the bulbar conjunctiva and extending to the cornea. "We speculated that these highly expressed circRNAs may increase the expression of FN1, SDC2, and MEX3D by sponging miR-200b-3p and further promote pterygium formation and growth." (PMID 36398070, 2022).
rectal cancer (1 paper, 2020). A primary or metastatic malignant neoplasm that affects the rectum. "SDC2 could regulate cell proliferation and recruit immune cells, and the level of SDC2 methylation in fecal DNA could be a diagnostic method for early colonel rectal cancer." (PMID 32793117, 2020).
rheumatic-disease (1 paper, 2005). "In the whole genome analysis of rheumatic-disease-susceptibility loci in MRL/lpr mice, Sdc2 (encoding syndecan 2) was a candidate gene for progressive arthritis." (PMID 15987484, 2005).
T-cell leukemia (1 paper, 2018). A malignant disease of the T-lymphocytes in the bone marrow, thymus, and/or blood. "To assess whether miR-126-3p was able to regulate these putative target genes, we transfected the T-cell leukemia cell line Jurkat with a miR-126-3p mimic and we evaluated the impact of its ectopic expression on AKT2, PPP3CB, RANKL, and SDC2 transcript levels." (PMID 29850558, 2018).
uterine corpus endometrial carcinoma (1 paper, 2020). A endometrial carcinoma (disease) that involves the body of uterus. "On the other hand, TCGA somatic samples carrying both NF1 and SDC2 mutations are scarce (N = 14/10,437), most of them (57.1%) also related to uterine corpus endometrial carcinomas." (PMID 32858845, 2020).
tumor (92 papers, 2008 to 2025). "SDC2, a member of the syndecan family, regulates cell adhesion and migration, and has been linked to tumor cell invasiveness." (PMID 40051633, 2025). "High SDC2 expression in CAFs is linked to aggressive phenotypes and poor survival, with SDC2 overexpression in CAFs contributing to tumor growth." (PMID 40075643, 2025). "Syndecan-2, which is expressed on tumor-associated stromal cells in breast tumors, contributes to metastasis and immune evasion." (PMID 38761292, 2024). "We next explored the possible mechanisms underlying the functional roles of SDC2 in GC severity and tumor progression." (PMID 37496999, 2023). "The shed SDC2 enhances tumorigenic activity by increasing the crosstalk of cancer cells with tumor-associated macrophages and endothelial cells to enhance angiogenesis for colon cancer progression via producing VEGF." (PMID 36358833, 2022). "SDC2 enhances TGF-β signaling in tumor-associated stromal cells and mediates immune evasion in breast cancer." (PMID 36358833, 2022). "Reduced levels of SDC2 in TASCs was associated with a significant decrease in tumour growth compared to that of shControl tumours and reduced levels of TGFβ‐regulated genes, for example, SMAD7." (PMID 33152121, 2021). "CD148 interacts with shed syndecan-2 in endothelial cells, causing changes in β1 integrin activation state, which leads to angiogenesis inhibition, affecting tumor growth." (PMID 26558271, 2015). "SDC2 overexpression in breast, colon and pancreatic tumour cells, is associated with altered cell morphology, focal adhesion formation, spreading, enhanced migration and invasion capabilities, and overall to a more aggressive tumour cell behaviour and disease progression." (PMID 33494442, 2021). "Our previous studies supported that in addition to IRF1, TMEM230, RNASET2, and SDC2 have tumor promoting and inhibiting functions." (PMID 40862725, 2025). "An investigation found that decreasing SDC2 expression in MDA-MB-231 cells resulted in a decrease in tumor size and a significant improvement in survival outcomes in a xenograft mouse model." (PMID 40940401, 2025). "SDC2 appears to play a distinctive role in the progression of cancer, as a wide range of evidence indicates that it promotes tumor development." (PMID 40940401, 2025). "Specifically, high expression of MDK in tumor cells likely engages SDC2 and NCL, both abundantly expressed on fibroblasts, to mediate these interactions." (PMID 40787466, 2025). "In contrast, qRT-PCR showed reduced SDC2 (P < 0.01) and FN (P < 0.05) mRNA levels in tumor tissues of pLNM patients compared to nLNM." (PMID 40940401, 2025). "SDC2 on this subgroup can interact with MMP2 on tumor-associated fibroblasts and endothelial cells, promoting tumor growth and metastasis." (PMID 39308672, 2024). "In humans, it has been proved that SDC2 is involved in tumor angiogenesis that facilitates tumor growth and metastasis." (PMID 39765460, 2024). "Methylation of SDC2 leads to transcriptional silencing, disrupted cell growth and differentiation, and massive proliferation of tumor cells, exhibiting strong invasive activity and metastatic characteristics." (PMID 39717169, 2024). "A study revealed that the inhibition of SDC2 expression in MDA-MB-231 cells diminished tumor volume and improved the survival of a xenograft mouse model." (PMID 36980680, 2023). "Altogether, these data demonstrated that depletion of SDC2 suppressed the growth of GC tumor xenografts in vivo." (PMID 37496999, 2023). "Another study found that SDC2 was 100% methylated in premature tumor tissue, 90.6% methylated in adenomatous stage tissue, and 90.9% methylated in proliferative polyp tissue, while no methylation was detected in normal tissue." (PMID 37881109, 2023). "We then examined the effects of SDC2 on GC tumor progression in vivo by establishment of tumor xenograft mouse models using SNU-719 and HGC-27 cells with or without SDC2 knockdown." (PMID 37496999, 2023).